MTOR (mechanistic target of rapamycin kinase)
Diseases named in the same sentence as MTOR in open-access papers (continued):
Sharing a sentence is not in itself a finding about the gene and the disease.
leukemia (continued). "We found that JAK2V617F mutated human and murine leukemia cell lines are sensitive to mTOR inhibitors showing a dose-dependent inhibition of cell proliferation and clonogenic potential that mainly reflected a cytostatic rather than an apoptotic effect." (PMID 23382981, 2013). "Aberrant PI3K/AKT/mTOR signaling has been linked to oncogenesis and therapy resistance in various malignancies including leukemias." (PMID 24244612, 2013). "Both Raf/MEK/ERK and PI3K/Akt/mTOR pathways are frequently activated in leukemia and other hematopoietic disorders caused by genetic mechanisms, playing an important role in the regulation of cell survival and proliferation." (PMID 22859971, 2012). "Alternatively, presence of cGVHD and use of Sir may be protective against AML relapse due to the enhanced graft-versus-leukemia effect conferred by cGVHD and inhibition of the mTOR pathway by Sir, especially in high-risk patients." (PMID 41254192, 2026). "However, the JAK/STAT and PI3K/AKT/mTOR pathways are constitutively activated in many cancers, including leukemia, due to the fact of genetic events such as mutations in cytokine receptors and aberrant chromosomal translocations." (PMID 35337104, 2022). "Downregulation of Mcl-1, a BCL-2 related antiapoptotic protein with PI3K/mTOR inhibitors may underlie the potentiation of the effect of Venetoclax, in leukemia cells." (PMID 34109125, 2021). "Considering the less than sufficient sample size for the pooled analysis of leukemia and the potential genetic relationship between mTOR gene expression and the rs2295080 polymorphism, relevant population-based clinical investigations by clinicians and researchers are warranted." (PMID 32597485, 2020). "Similarly, mTOR overexpression in leukemia cells was associated with resistance to NTS-induced cell death." (PMID 32131492, 2020). "This review highlights experimental evidence underlying the molecular mechanisms of mTOR inhibitors and summarizes their evolving role in the treatment of hematologic disease, including leukemia, lymphoma, myeloma, immune hemocytopenia, and graft-versus-host disease (GVHD)." (PMID 33489922, 2020). "Based on these results, we suggest that NTS could be used as a novel therapeutic for leukemia, which acts through mTOR K48-linked ubiquitination and degradation in a phosphorylation-dependent manner." (PMID 32131492, 2020). "Furthermore, the cumulative Z-curve of leukemia risk did not exceed either the TSA monitoring boundary or the RIS line, suggesting the need for more evidence for the association between mTOR rs2295080 and the risk of leukemia." (PMID 32597485, 2020). "Interestingly, genes with a higher expression in the CIMP− subgroup were enriched in the mTOR signaling pathway which has been shown associated with increased leukemia‐propagating potential in individual T‐ALL clones." (PMID 30575306, 2019). "In a preclinical setting treating individual patient-derived ALL in vivo, mTOR inhibition alone, and even more pronounced together with conventional remission induction therapy, significantly delayed post-treatment leukemia reoccurrence in TTLshort/high-risk ALL." (PMID 25682198, 2015). "mTOR has attracted widespread attention as a target for cancer therapy and several variants of the original mTOR inhibitor rapamycin are being evaluated in clinical trials, both for solid tumors and leukemias." (PMID 24073922, 2013). "Moreover, recent reports have shown that mTOR inhibition effectively suppresses neuronal hypertrophy, endometrial hyperplasia and leukemia initiation after tissue-specific Pten loss or in the Pten+/− mice." (PMID 18043744, 2007). "Emerging evidence suggests that this pathway may interact with the PI3K/Akt/mTOR pathway, which is known as a modulator of cell growth, metabolism, and survival, and its dysregulation is often associated with leukemia, where it drives clonal expansion of malignant cells." (PMID 39996741, 2025).
leukemia (continued). "To further our understanding of Ki-67 ̄ leukaemia cells, particularly with regard to their metabolic activity and hence potential susceptibility to therapeutic inhibition of this activity, we have measured biomarkers of mTOR activation status in presentation samples, using flow cytometry." (PMID 26985829, 2016). "Therefore, inhibiting the mTOR/HIF-1 metabolic/signalling axis could be an excellent therapeutic strategy for treating human disorders associated with myeloid cell function – leukaemia, autoimmune disease, and allergy." (PMID 26384306, 2015). "Single cell phospho-flow analysis of structure-activity relationships for the rocaglate natural product family identifies molecular features responsible for mTOR and DNA damage activity in leukemia cells." (PMID 40745386, 2025). "Many studies have shown that the PI3K/Akt/mTOR signalling pathway plays a crucial role in the treatment of various cancers, leukaemia, cardiovascular and cerebrovascular diseases and other diseases." (PMID 40421249, 2025). "Chemical screening data suggest potential therapeutic synergy between USP30 inhibitors and AKT/mTOR pathway inhibitors for leukemia treatment, positioning USP30 as a novel therapeutic target requiring further investigation in combinatorial regimens." (PMID 40918504, 2025). "We analyzed the expression of the PIK3CA, AKT1, and mTOR genes across various leukemia cell lines using the Human Protein Atlas database, with a specific focus on the HL-60 cell line, which was employed in our study." (PMID 40917720, 2025). "Glycometabolic adaptation mediated by Akt/mTOR/c-Myc signaling has been confirmed to facilitate the insensitivity of drug resistant leukemia cells to adriamycins." (PMID 40612109, 2025). "Collectively, these data indicate that mTOR signalling has a key role downstream of taurine in leukaemia cells." (PMID 40369079, 2025). "This review aims to explore the involvement of the Hedgehog and PI3K/Akt/mTOR pathways in leukemias, with a focus on their crosstalk and impact on cell death mechanisms." (PMID 39996741, 2025). "Mechanistically, we identify a critical requirement of taurine from the microenvironment in regulating mTOR-driven glycolysis in leukaemia cells." (PMID 40369079, 2025). "Inhibition of Plk1 activity by the Plk1 inhibitors volasertib effectively reduced the phosphorylation of AKT, mTOR and S6 in leukemia and Burkitt lymphoma cells." (PMID 40166466, 2025). "In-vitro experiments demonstrated that TIP39 induces autophagy in leukemia cells by inhibiting mTOR, thereby reducing leukemia cell apoptosis." (PMID 41585794, 2025). "We aimed to describe the effects of JR-AB2-011 in leukemia/lymphoma cells, where the mTOR pathway is often aberrantly activated." (PMID 39259491, 2024). "We found that hyperactivation of the LAPTM4B-driven mTOR pathway was crucial for the growth of EVI1hi leukemia cells." (PMID 39680456, 2024). "Several classes of mTOR inhibitors such as rapalogues or second-generation mTOR inhibitors have been evaluated in clinical trials for leukemia treatment." (PMID 39000261, 2024). "Dysregulation of the PI3K/Akt/mTOR pathway (phosphoinositide 3-kinase (PI3K)/Akt/mammalian target of rapamycin (mTOR)) as one of the TGF-β intracellular signals has been reported in leukemia." (PMID 37692500, 2024). "For example, nilotinib, an FDA-approved drug for leukemia, induced autophagy via mTOR inhibition, and reduced amyloid plaques and improved cognition in AD model Tg-APP mice." (PMID 39454957, 2024). "The promotion of autophagy by DHRSX involves the downregulation of AKT/mTOR phosphorylation and the upregulation of beclin-1, which are highly related to the antiapoptotic function and chemotherapy resistance of leukemia cells." (PMID 38811988, 2024). "Meanwhile, both CEP and tetrandrine induced apoptosis through caspase cascade regulation, cell cycle arrest, MAPK activation and PI3K/Akt/mTOR signal modification in GC resistant human leukemia Jurkat T cells." (PMID 38734604, 2024).
leukemia (continued). "SMG1 is a potential tumor suppressor that can antagonize mammalian target of rapamycin (mTOR) to regulate leukemia cell growth in acute myeloid leukemia." (PMID 37313458, 2023). "Inhibitors of the PI3K/Akt/mTOR pathway have been used in leukemia treatment since 2014, and some of them have improved treatment outcomes in clinical trials." (PMID 37958470, 2023). "Yanjun Han, Mechanism of ginsenoside Rg1 induced aging in human leukemia cells (K562) based on PI3K/Akt/mTOR autophagy pathway, 2020, Dali University." (PMID 37600717, 2023). "In conclusion, our data demonstrate that the combination of two promising anti-leukaemia approaches using mefloquine or mTOR inhibition exceeds by far the reported effects of a single treatment without any detectable increase in the toxicity." (PMID 36816923, 2023). "Collectively, these findings support the use of mTOR inhibitors as a therapeutic option in leukemia." (PMID 37775560, 2023). "PI3K/AKT/mTOR was confirmed to be a critical oncogenic signaling pathway in AML leukemia stem cells (LSCs)." (PMID 36621846, 2023). "Clinical trials are already underway or completed for drugs like, AKT inhibitor, MK-2206, for CLL/SLL and relapse/refractory leukemias or lymphomas, while mTOR inhibitors sirolimus (rapamycin) and everolimus are being used in clinical trials." (PMID 36694243, 2023). "In chronic lymphocytic leukemia (CLL), AKT inhibitors and mTOR inhibitors (Torin-1) effectively restore CMA activity while removing prooncogenic proteins involved in leukemia initiation and progression." (PMID 37180758, 2023). "In summary, NUP98-PMX1;Abl1−/− cells were highly sensitive to PI3K and mTOR inhibitors when compared to the Abl1 + /+ counterparts, and imatinib sensitized Abl1 + /+ leukemia cells to PI3K inhibitor buparlisib." (PMID 36959186, 2023). "The expression of proteins related to apoptosis and autophagy, including cleaved-PARP-1, Bcl-2, Bax, LC3-I/II, Beclin-1, Atg5, p62, phospho-AMPK, AMPK, phospho-mTOR, mTOR, phospho-Akt, and Akt, in human leukemia cells were evaluated using Western blotting." (PMID 36826047, 2023). "PMTZ induces cell death in leukemia by activating AMPK and inhibiting the PI3K/AKT/mTOR pathway, leading to autophagy-associated apoptosis." (PMID 38074670, 2023). "Nowadays, the Food and Drug Administration (FDA) has approved two inhibitors of the PI3K/Akt/mTOR pathway for leukemia treatment; these are Idelalisib and Duvelisib, for the treatment of CLL." (PMID 37958470, 2023). "Constitutive activation of JAK/STAT and PI3K/Akt/mTOR signaling pathways are crucial in the pathogenesis of leukemia." (PMID 36145344, 2022). "Clioquinol can trigger pro-death autophagy via interrupting mTOR signaling pathway in leukemia and myeloma cells, which not only inhibits enzymatic activity of mTOR (a critical modulator of autophagy) as rapamycin, but also suppresses the expression of mTOR." (PMID 36465935, 2022). "Hyperactivation of the PI3K/Akt/mTOR pathway is crucial for the development of various malignancies, including leukemia." (PMID 36145344, 2022). "The JAK/STAT and PI3K/AKT/mTOR pathways are constitutively activated in leukemia leading to c-Myc overexpression." (PMID 35337104, 2022). "Our findings further demonstrated that a combination of 8-GL and mTOR inhibitor synergistically curbs tumor growth and extends mice survival in a systematic leukemia model." (PMID 36437247, 2022). "Based on our current findings, it can be concluded that TQ-induced growth inhibition of leukemia cells was associated with reduced expression of PI3K, Akt, and mTOR genes and re-expression of PTEN gene at the mRNA and protein levels." (PMID 36145344, 2022). "In leukemia treatment, PPA induced apoptosis through caspase cascade regulation, cell cycle arrest, MAPK activation, and PI3K/Akt/mTOR signaling modification, showing cytotoxic effects on glucocorticoid-resistant human leukemia Jurkat T cells." (PMID 35684449, 2022).
leukemia (continued). "Therapeutic targeting of the mTOR pathway as an anticancer strategy for leukemia has been under extensive investigation." (PMID 35579750, 2022). "Among the most studied pathways regulating HSC homeostasis, the Akt-mTOR network is critical for self-renewal, survival, and differentiation and prevents the transformation of HSCs into leukemia stem cells." (PMID 35526025, 2022). "This study investigated the effects of thymoquinone (TQ), a bioactive constituent in Nigella sativa, on the activation of upstream regulators of c-Myc: the JAK/STAT and PI3K/AKT/mTOR pathways in HL60 leukemia cells." (PMID 35337104, 2022). "In short, combining USP30 inhibitors with AKT/mTOR compounds in treating leukemia warrants further investigation." (PMID 35250566, 2022). "The use of PI3K/AKT/mTOR inhibitors downregulates c-Myc expression and enhances the anti-leukemic effects of the leukemia drug, all-trans retinoic acid (ATRA), in AML cell lines and primary patient samples." (PMID 35337104, 2022). "In HSCs, the deletion of Pten, a repressor of mTOR, or constitutive activation of mTOR, lead to ectopic proliferation of transit-amplifying progenitors, resulting in leukemia." (PMID 35433828, 2022). "The phosphorylation of AKT and MTOR was markedly reduced after the in vivo treatment with torin-1 in mouse E2A-PBX1+ leukemia cells." (PMID 35794338, 2022). "EZH2 has a bidirectional tumorigenic effect involving mTOR signaling, as shown in EZH2-deficient leukemia cells." (PMID 36686830, 2022). "IKZF1 and IL7R synergistically activated downstream JAK/STAT5 and PI3K/Akt/mTOR signaling pathways to promote leukemia." (PMID 35419036, 2022). "In AML, dysregulation of these processes aids leukemia cells in enhancing growth and proliferation and resisting apoptosis; increased mTOR activity thus plays a role in AML relapse and initiation." (PMID 33401428, 2021). "The aggregated collection of pathways highlights the mTOR –pathway, which plays a critical role in leukemia initiation." (PMID 33802234, 2021). "Gedatolisib (WYE-129587/PKI-587/PF-05212384), a PI3Kα/mTOR inhibitor, has been investigated in preclinical leukemia models, including T-ALL and Ph-like ALL, with very good results." (PMID 33401428, 2021). "To compare different mTOR inhibitors alone or in combination with dasatinib, we used the p190 cell system in which primary murine leukemia cells are generated from bone marrow using a retroviral vector expressing p190-BCR-ABL." (PMID 34737376, 2021). "Based on IHC and flow cytometry data, higher mTOR activity, especially in the presence of a high amount of mTORC2 complex, was correlated with worse prognosis and lower OS in lymphoma/leukemia patients." (PMID 35029792, 2021). "Data showed that in vivo treatment of primary xenografts with the CK2 inhibitor, CX-4945, in combination with rapamycin, results in the inhibition of mTOR pathway and reduced transcription of the MTOR gene in leukemia cells in both BM and spleen." (PMID 33531656, 2021). "It was found that the rapamycin derivatives inhibit AKT signaling in primary AML cells both in vitro and in vivo, supporting the therapeutic potential of mTOR inhibition strategies in leukemias and multiple myeloma dissemination and angiogenesis." (PMID 33828590, 2021). "High-throughput drug sensitivity and resistance testing revealed leukemia cells from RUNX1mut patients to be highly responsive for mTOR-, BCL2-, and VEGFR inhibitors and glucocorticoids." (PMID 32782381, 2021). "The PI3K/AKT/mTOR signaling network is hyperactivated in leukemia and includes a number of kinases that are potential drug targets." (PMID 34737376, 2021). "Here, we report that IKAROS represses MTOR transcription and IKAROS’ ability to repress MTOR in leukemia is impaired by oncogenic CK2 kinase." (PMID 33531656, 2021).
leukemia (continued). "Suppose there is a direct link between the mTOR pathway, autophagy and apoptosis following cannabinoid treatment in leukemia cells, as there is in glioblastoma or hepatocellular carcinoma; it is still to be investigated." (PMID 33466435, 2021). "Nonetheless, it is important to conclude cautiously on the effects of such treatments in our leukemic mouse model, since mTOR inhibitors likely affect leukemia progression and per se reduce the pressure on NK cells." (PMID 34975835, 2021). "Altogether, these data show a possible benefit of PI3K/AKT/mTOR inhibition as a therapeutic approach for MLL-rearranged leukaemia." (PMID 34109125, 2021). "NGDN encodes the E1F4E binding protein and, in leukemia cell lines, NGDN knockdown activates the mTOR pathway." (PMID 34400688, 2021). "The microRNA—miR-150, miR-34a, and miR-29b—have also shown significant anti-leukaemia effects by targeting wnt-signalling, mTOR signalling pathways, MYC, and Sp1/FUT4-fucosylations." (PMID 34207299, 2021). "The mTOR, downstream effector of PI3k, can make leukaemia-initiating cells acquire the properties of proliferation and survival and eliminate haematopoietic stem cell." (PMID 34426610, 2021). "In the early 2010s, our and others’ results confirmed that elevated mTOR activity is characteristic for human lymphoma and leukemia cells." (PMID 35029792, 2021). "Another pathway that has been identified in the development of ALL includes the phosphatidylinositol 3-kinase (PI3K)/AKT/mTOR pathway, which is known to promote the survival and proliferation of leukemia cells, especially in T-ALL." (PMID 34830969, 2021). "In this study, we show that NTP-treated solutions (NTS) can induce death in various leukemia cells through mechanistic target of rapamycin (mTOR) ubiquitination." (PMID 32131492, 2020). "The altered expression of HMGA2 in AMLs is coherent with the already known oncogenic role of mTOR and Akt in leukemias." (PMID 32503270, 2020). "The inhibitors of PI3K-Akt-mTOR axis have shown preliminary anti-leukemia effects against AML both in vivo and in vitro." (PMID 32883226, 2020). "The results showed that multiple neoantigen proteins participated in AMPK, MAPK, mTOR signaling pathways which are key players in occurrence and development of leukemia from which Jurkat cell line was originated from." (PMID 32241270, 2020). "Consistent with these two mechanisms, DHA induces the lethal ROS accumulation and ferroptosis of leukemia cells through the AMPK/mTOR pathway." (PMID 32322334, 2020). "A potential strategy to overcome this drawback is to identify mTOR-responsive leukemias at diagnosis and incorporate lower doses of an mTOR inhibitor staggered to the chemotherapy backbone." (PMID 32235787, 2020). "In NTS-treated leukemia cell lines, mTOR bands were observed at a high molecular weight, likely due to post-translational modification (PTM) events, such as ubiquitination, while total mTOR gene expression was not affected." (PMID 32131492, 2020). "In particular, the oncogenic activation of mTOR pathways seen in leukemia patients contributes to chemotherapy resistance, disease progression, and poor prognosis." (PMID 32131492, 2020). "The complex formed between TrkA and c-Src has been detected in leukemia, while the inhibition of c-Src suppressed the Akt/mTOR pathway." (PMID 33330048, 2020). "Pervious study has reported that inhibition of Aurora kinases induced apoptosis and autophagy in leukemia cells via AURKB/p70S6K/RPL15 axis with the involvement of PI3K/Akt/mTOR, AMPK, and p38 MAPK signaling pathways." (PMID 32194783, 2020). "NTS-induced mTOR ubiquitination and degradation were shown to have crucial roles in leukemia cell death." (PMID 32131492, 2020). "RNF126 strongly induced mTOR ubiquitination in both wild type and K48 ubiquitin-overexpressing leukemia cells." (PMID 32131492, 2020).